ADNP (activity dependent neuroprotector homeobox)
Diseases named in the same sentence as ADNP in open-access papers (continued):
Sharing a sentence is not in itself a finding about the gene and the disease.
ADNP syndrome (34 papers, 2017 to 2025). "Our work supports this idea and adds to our understanding of the biology of ADNP syndrome by investigating the specific effect of ADNP loss in microglia." (PMID 39605704, 2024). "When one of the two copies of the ADNP gene is mutated and loses its normal function, the ADNP syndrome occurs, characterized by intellectual disability and global developmental delay which includes both language and motor domains." (PMID 38673966, 2024). "Mutations in the gene encoding ADNP underlie ADNP syndrome, which is characterized by neurological and developmental abnormalities." (PMID 37285842, 2023). "We conclude that heterozygous ADNP mutations that cause ADNP syndrome result in both R-loop and CTCF alterations across the genome." (PMID 35013239, 2022). "In ADNP syndrome, for instance, two distinct episignatures have been identified, as a result of truncating variants in two distinct protein domains of the ADNP gene." (PMID 35887345, 2022). "As such, de novo mutations in the ADNP gene lead to ADNP syndrome (also known as Helsmoortel Van Der As syndrome), which is characterized by autistic/intellectual disability." (PMID 36230962, 2022). "Activity-dependent neuroprotective protein (ADNP) syndrome is an autistic-like disorder caused by mutations of the human ADNP gene." (PMID 34285320, 2021). "The gRNA sequence was designed to target the Tyr719* residue located in exon 6 of the ADNP gene, one of the major point mutations that cause ADNP syndrome." (PMID 34285320, 2021). "Activity-dependent neuroprotective protein (ADNP) mutations are linked with cognitive dysfunctions characterizing the autistic-like ADNP syndrome patients, who also suffer from delayed motor maturation." (PMID 33086621, 2020). "Delayed motor development characterizes a large majority (96%) of ADNP syndrome children, suffering from de novo mutations in ADNP." (PMID 32937737, 2020). "In summary, we discovered ADNP deficiency associated changes in commensal gut microbiota compositions, a sex-dependent biomarker for the ADNP syndrome and beyond." (PMID 32072336, 2020). "De novo mutations in ADNP result in the ADNP syndrome, with children suffering from severe global developmental delays that affect the central and peripheral nervous systems." (PMID 33086621, 2020). "Given potential interactions between the microbiome and brain function, we now investigated the potential effects of the ADNP-deficient genotype, mimicking the ADNP syndrome on microbiota composition in the Adnp+/– mouse model." (PMID 32072336, 2020). "Specifically, cellular expression of heterozygous ADNP truncating mutations (representing the majority of the ADNP syndrome cases, e.g., ADNP p.Ser404* or p.Tyr719*, or p.Arg730*) reduced Tau–MT interactions and impaired MT dynamics, in cell culture models." (PMID 33329371, 2020). "Following the positive screen for ADNP syndrome, ADNP was sequenced and a pathogenic variant was detected (c.2491_2494del; p.Leu831Ilefs*82)." (PMID 31029150, 2019). "The patient carried an ADNP p.Tyr719* causal heterozygous truncating mutation, identified in other 23 children with ADNP syndrome from more than 100 cases diagnosed worldwide." (PMID 30679581, 2019). "ADNP syndrome (also known as Helsmoortel-Van Der Aa Syndrome) is a monogenic neurodevelopmental disorder caused by mutations in activity-dependent neuroprotective protein (ADNP)." (PMID 39054328, 2024). "From a translational medicine point of view, our findings are also in agreement with results obtained with mouse models of the autistic/intellectual disability known as ADNP syndrome in which patients suffer from speech delays and language impairment because of ADNP mutations." (PMID 37845254, 2023). "Furthermore, recent studies in the Gozes laboratory identified somatic mutations in ADNP in Alzheimer’s disease brains correlating with the progression of Tau pathology, and paralleled by Tau depositions in the ADNP syndrome young postmortem brain." (PMID 35399934, 2022).
ADNP syndrome (continued). "Importantly, patient-derived hiPSCs that contain ADNP Y719* mutation show severely reduced protein levels and R-loop accumulation at ADNP targets, arguing for haploinsufficiency as the cause for ADNP syndrome." (PMID 35013239, 2022). "Importantly, the mutated (mostly truncated) and the intact ADNP alleles are both expressed in ADNP syndrome human cells, supporting the Adnp+/− mouse as a model predictive for ADNP heterozygous mutation deficiency in humans." (PMID 33329371, 2020). "ADNP (Activity Dependent Neuroprotective Protein) is a neuroprotective protein whose aberrant expression has been frequently linked to neural developmental disorders, including the Helsmoortel-Van der Aa syndrome (also called the ADNP syndrome)." (PMID 32533114, 2020). "Activity-dependent neuroprotective protein (ADNP), discovered and first characterized in our laboratory (IG), is vital for mammalian brain formation and presents one of the leading genes mutated de novo causing an autistic syndrome, namely the ADNP syndrome." (PMID 31534115, 2019). "Thus, ADNP is a key regulator of sex-dependent neurogenesis that acts by controlling canonical pathways, with NAP compensating for fundamental ADNP deficiencies, striding toward clinical development targeting the ADNP syndrome and related neurodevelopmental/neurodegenerative diseases." (PMID 39715923, 2025). "Furthermore, de novo mutations in the ADNP gene are associated with ADNP syndrome (also known as Helsmoortel Van Der Aa syndrome), which manifests a variety of clinical symptoms, including global developmental delays, autistic/intellectual disability, and motor dysfunctions." (PMID 38673966, 2024). "Helsmoortel–Van der Aa syndrome (HVDAS) is a rare genetic disorder caused by variants in the activity-dependent neuroprotector homeobox (ADNP) gene; hence, it is also called ADNP syndrome." (PMID 38254177, 2024). "Activity-dependent neuroprotective protein (ADNP) syndrome is a rare neurodevelopmental disorder resulting in intellectual disability, developmental delay and autism spectrum disorder (ASD) and is due to mutations in the ADNP gene." (PMID 39054328, 2024). "Similar to the ADNP syndrome, the ADNP haploinsufficient mouse shows low synapse density, leading to motor and cognitive ability delays." (PMID 38673966, 2024). "De novo variants in the activity-dependent neuroprotector homeobox (ADNP) gene can result in Helsmoortel–Van der Aa syndrome (HVDAS; OMIM 615873), also referred to as ADNP syndrome." (PMID 38254177, 2024). "Deletion of the Adnp in mice leads to compromised brain formation and embryonic lethality, and mutations in ADNP underlie the complex neurological and developmental disorder ADNP syndrome (Helsmoortel-Van der Aa autism syndrome, ADNP-related disorder)." (PMID 37285842, 2023). "One of the most consistently enriched proteins was activity-dependent neuroprotective protein (ADNP), which is frequently mutated in ASD and causal in ADNP syndrome." (PMID 35013239, 2022). "Interestingly, ADNP/NAP preferentially interact with the alternatively spliced three microtubule binding repeat dynamic Tau (associated with development) compared with four microtubule binding repeat Tau17 implicating potential early onset tauopathy in association with the ADNP syndrome." (PMID 32661233, 2020). "Recently, ADNP was found to be mutated de novo in 0.17% of autism spectrum disorder (ASD) cases, thus causing the ADNP syndrome." (PMID 31992971, 2019). "The two predominantly opposite methylation signatures in ADNP syndrome (the ADNP-1 episignature is largely hypomethylated; the ADNP-2 episignature is hypermethylated) lead us to suspect that each mutation sub-group has unique cellular consequences." (PMID 31029150, 2019). "ADNP syndrome (Helsmoortel-van der Aa syndrome; OMIM# 615873) is caused by dominant negative truncating variants in ADNP." (PMID 31029150, 2019).
ADNP syndrome (continued). "One such area occurs in PACSIN1, which showed hypomethylation in all ADNP syndrome samples and has a considerable overlap in cellular function with ADNP." (PMID 31029150, 2019). "Most recently, novel ADNP syndrome mice have been developed using CRISPER-Cas9 gene editing technology to produce mice heterozygous for Adnp pTyr718* (Tyr), a paralog of the most common ADNP mutation, which have Tyr-specific sex differences." (PMID 36429060, 2022). "Notably, patient-derived human induced pluripotent stem cells that contain an ADNP syndrome-causing mutation exhibit R-loop and CTCF accumulation at ADNP targets." (PMID 35013239, 2022). "Additionally, patient-derived human induced pluripotent stem cells that contain the prevalent ADNP syndrome-causing mutation p719* exhibit R-loop and CTCF accumulation at ADNP targets." (PMID 35399934, 2022). "Activity dependent neuroprotective protein (ADNP) syndrome (OMIM: 615873) is an autosomal dominant neurodevelopmental disorder characterized by mild-to-severe intellectual disability (ID), autism spectrum disorder (ASD), speech and motor delays, and a variety of medical comorbidities." (PMID 33673501, 2021). "ADNP showed relatively reduced expression in the ADNP syndrome cerebellum, which was also observed for 25 additional genes (representing >50% of the tested genes), including NLGN1, NLGN2, PAX6, SMARCA4, and SNAP25, converging on nervous system development and tauopathy." (PMID 32661233, 2020). "On the other hand, decreases in ADNP levels have been linked with diminished dendritic spines and synaptic plasticity in mice and cognitive deficiencies in mice and humans, with most if not all ADNP syndrome patients suffering from intellectual disabilities." (PMID 36230962, 2022). "Notably, the involvement of ADNP in cognitive performance is not limited to the ADNP syndrome but is extended to schizophrenia and Alzheimer's disease with ADNP transcripts dysregulated in lymphocytes in both diseases and with ADNP blood levels correlating with intelligence." (PMID 30534048, 2018). "This is not a surprise, considering that the ADNP syndrome, also known as Helsmoortel–Van der Aa syndrome (HVAS) caused by ADNP mutations, is characterized by multiple clinical symptoms, including ophthalmic alterations." (PMID 37108060, 2023). "Therefore in the case of ADNP syndrome, it may be most useful to explore the limited DMRs with shared epigenetic patterns between ADNP-1 and ADNP-2 episignatures." (PMID 31029150, 2019).
Alzheimer disease (24 papers, 2015 to 2025). A progressive, neurodegenerative disease characterized by loss of function and death of nerve cells in several areas of the brain leading to loss of cognitive function such as memory and language. "ADNP mutations have been detected in AD brains, and ADNP is neuroprotective in Alzheimer ́s disease models, while reduced retinoic acid synthesis has been related to AD and other brain disorders." (PMID 39485512, 2024). "In turn, tauopathy correlates with decreased cognition and ADNP levels, and increased somatic mutation loads in the aging/human Alzheimer’s disease brain." (PMID 36945042, 2023). "The NAP ADNP motif, furthermore, binds to the armadillo domain of beta-catenin, important for ADNP neurodevelopmental/maintenance functions, and linked with Alzheimer’s disease (AD) amyloid/Tau pathology." (PMID 37845254, 2023). "Multiple de novo pathological mutations in ADNP cause the autistic ADNP syndrome, and they have been further suggested to affect Alzheimer’s disease progression in a somatic form." (PMID 36230962, 2022). "Other diseases of the synapse where deficiencies in ADNP or microbiome were observed include for example, Alzheimer’s disease (AD), Parkinson’s disease (PD), schizophrenia, and attention deficit hyperactivity disorder (ADHD) as follows." (PMID 32072336, 2020). "Furthermore, we discovered an accumulation of somatic mutations in the ADNP gene in post-mortem Alzheimer’s disease brains and correlated this accumulation with increased severity of tauopathy." (PMID 36230962, 2022). "Furthermore the recurrent somatic ADNP frameshift mutation p.Arg730Thrfs*4, which is one of the pathogenic mutations in ADNP that is correlated to aging/Alzheimer’s disease, truncates ADNP length to a protein of 734aa." (PMID 35399934, 2022). "Furthermore, our recent findings also associated somatic brain mutations in ADNP (among other genes) as possible risk factors/driving pathologies of Alzheimer’s disease (the most prevalent tauopathy)." (PMID 32661233, 2020). "In the OpenTargets database, alterations in ADNP have been associated with autism spectrum disorders, intellectual disability, dysmorphic features, and hypotonia, JUN with Alzheimer's disease, and PRDM14 with schizophrenia." (PMID 36414996, 2022). "The vast majority of studies have focused on the role of ADNP in neurological diseases including autism spectrum disorder and Alzheimer's disease." (PMID 31767542, 2019). "ADNP suppresses its own transcription, and lymphocyte ADNP was found to be upregulated in Alzheimer’s disease and in schizophrenia patients in a sex-dependent manner." (PMID 31534115, 2019). "Subsequent studies have shown that ADNP is dysregulated in schizophrenia and Alzheimer’s disease (AD), and mutated in autism spectrum disorder (ASD) with 0.17% prevalence (together, these ASD cases are now identified as the ADNP syndrome)." (PMID 31632241, 2019). "ADNP/ADNP2 control of erythropoiesis and ADNP/ADNP2 coregulation with dysregulation association with aging, as well as brain disorders, such as schizophrenia and Alzheimer’s disease." (PMID 39251453, 2024). "Importantly, ADNP is essential for brain formation, with deficits in ADNP leading to autistic/intellectual disability-like and Alzheimer’s disease-like features in mice." (PMID 36230962, 2022). "Interestingly, sexual differences were found in ADNP expression in Alzheimer’s disease (lymphocytes) and in schizophrenia (post mortem brains and lymphocytes)." (PMID 33086621, 2020).
Alzheimer disease (continued). "Peripheral ADNP was also discovered as a biomarker for Alzheimer’s disease and schizophrenia, with nasal administration of the ADNP snippet peptide NAP (enhancing endogenous ADNP activity) leading to partial cognitive and functional protection at the cellular, animal and clinical settings." (PMID 30664622, 2019). "Furthermore, ADNP is the only protein significantly decreasing in the serum of Alzheimer’s disease (AD) patients." (PMID 27386198, 2015). "In particular, the down-regulation of ADNP may concur with dopaminergic neurodegeneration in Parkinson’s Disease, and the ADNP plasma/serum and lymphocyte mRNA levels were correlated to clinical stage and Alzheimer’s disease (AD) biomarkers." (PMID 36362439, 2022). "Interestingly, a secreted protein related to Alzheimer ́s disease and AIS proteins EB1/3, the Activity-Dependent Neuroprotective Protein (ADNP), was downregulated (log2(FC) = – 0.40 and – log10(p-value) = 2.81)." (PMID 39485512, 2024). "The observed decline in ADNP expression with age, coupled with the physiological distribution of HNP neurons in regions vulnerable to Alzheimer’s disease, suggests a critical link between macroscopic brain vulnerability and specific microscopic cellular components." (PMID 39766225, 2024). "Interestingly, sexual differences were found in ADNP, ADNP2 expression in Alzheimer’s disease (lymphocytes) and in schizophrenia (postmortem brains and lymphocytes)." (PMID 32937737, 2020). "Furthermore, clinical trials with the ADNP fragment NAP (the investigational drug davunetide) showed efficacy in women suffering from the tauopathy progressive supranuclear palsy and differentially boosted memory in men (spatial) and women (verbal), exhibiting prodromal Alzheimer’s disease." (PMID 39715923, 2025).
schizophrenia (22 papers, 2015 to 2025). A major psychotic disorder characterized by abnormalities in the perception or expression of reality. "Regarding schizophrenia, we showed that ADNP is linked with the regulation of autophagy, and we further showed that this process is disrupted in schizophrenia and corrected by NAP treatment." (PMID 32072336, 2020). "In human, ADNP is mutated in autistic children with cognitive deficits and is deregulated in schizophrenia." (PMID 28933765, 2017). "Moreover, NAP protects from autophagy in a mouse model of schizophrenia enhancing the interaction between ADNP and the MTs-associated protein 1 light chain 3 β (LC3B) and restoring Becn1 mRNA levels in the hippocampus." (PMID 28933765, 2017). "Human mutations of ADNP and ADNP2 are known to be associated with neural developmental disorders (NDDs), including autism spectrum disorders (ASDs) and schizophrenia (SZ)." (PMID 39273418, 2024). "Clinically, the ADNP-cocaine connection is especially relevant for individuals with deregulated ADNP, i.e., patients with autism spectrum disorder and patients with schizophrenia." (PMID 39251453, 2024). "In a Tg schizophrenia mouse model (activity-dependent neuroprotective protein (ADNP)+/− Tg mice), intranasal administration of NAP decreased brain levels of p-tau and improved cognition." (PMID 33329322, 2020). "The activity-dependent neuroprotective protein (ADNP) has been found deregulated in postmortem hippocampi of schizophrenia patients." (PMID 28933765, 2017). "A reduction of ADNP and its homologous protein, ADNP2, is observed in schizophrenic patients, and it is recapitulated in Map6-deficient (Map6+/−) mice, another transgenic model of schizophrenia." (PMID 30061532, 2018). "Furthermore, the VIP receptor, VPAC2, controlling ADNP expression, has been linked to schizophrenia and autism spectrum disorders and VIP regulates ADNP expression in vivo." (PMID 30534048, 2018). "We argued that “increased ADNP and ADNP2 expression in lymphocytes from schizophrenia patients compared to healthy controls and a negative correlation with disease duration may be a compensatory mechanism." (PMID 31191249, 2019).